NLRP3 (NLR family pyrin domain containing 3)
Diseases named in the same sentence as NLRP3 in open-access papers (continued):
Sharing a sentence is not in itself a finding about the gene and the disease.
cryopyrin-associated periodic syndrome (330 papers, 2007 to 2026). Cryopyrin associated periodic syndrome (CAPS) defines a group of autoinflammatory diseases, characterized by recurrent episodes of systemic inflammatory attacks in the absence of infection or autoimmune disease. "NLRP3 was identified because of its association with autosomal dominant autoinflammatory diseases (NLRP3-AIDs), also known as CAPSs (cryopyrin-associated periodic syndromes)." (PMID 40299348, 2025). "Cryopyrin-associated periodic syndromes (CAPS) encompass a spectrum of autoinflammatory disorders that result from dominant mutations in NLRP3, leading to hyperactivation of the NLRP3 inflammasome in monocytes and macrophages." (PMID 41168503, 2025). "Cryopyrin-Associated Periodic Syndromes (CAPS) are rare autoinflammatory diseases characterized by dysregulated activation of NLRP3 inflammasome and increased production of interleukin-1 (IL-1) beta, the main mediator of innate inflammation." (PMID 40748728, 2025). "For instance, gain-of-function mutations in the NLRP3 gene lead to uncontrolled inflammasome activation and excessive IL-1β production in cryopyrin-associated periodic syndromes (CAPS)." (PMID 41415279, 2025). "Serum IL-6 levels are elevated in humans and mice, with NLRP3 inflammasome-mediated diseases, such as cryopyrin-associated periodic syndromes (CAPS), a disease caused by mutations in the Nlrp3 gene." (PMID 39982672, 2025). "Cryopyrin-associated periodic syndrome (CAPS) is a condition characterized by dominant genetic variants in the NLRP3 gene, which lead to the formation of constitutively active inflammasomes." (PMID 40410596, 2025). "THL has also demonstrated efficacy against constitutively active NLRP3 mutations, such as those seen in cryopyrin-associated periodic syndromes (CAPS)." (PMID 40959087, 2025). "Clinically, NLRP3 has also been found to be associated with inflammatory skin diseases such as psoriasis, atopic dermatitis, urticaria, cryopyrin-associated periodic syndrome (CAPS), and vitiligo." (PMID 40006996, 2025). "Gain-of-function mutations within the NACHT domain of NLRP3 and neighboring regions are linked to 3 autosomal dominant periodic fever disorders collectively classified as cryopyrin-associated periodic syndromes (CAPS)." (PMID 39691768, 2024). "These clinical features are clearly different from NLRP3 GOF–inducing CAPS diseases (cryopyrin-associated periodic syndrome)." (PMID 38652550, 2024). "The list of NLRP-3 related SAIDs includes cryopyrin-associated periodic syndrome (CAPS), gout, and Crohn’s disease." (PMID 39097717, 2024). "Gain-of-function mutations in NLRP3 lead to abnormal spontaneous activation of the NLRP3 inflammasome, causing the dominant systemic autoinflammatory disease known as cryopyrin-associated periodic syndrome (CAPS)." (PMID 39333773, 2024). "Gain-of-function mutations in NLRP3 result in Cryopyrin-Associated Periodic Syndrome in human patients." (PMID 38321014, 2024). "Cryopyrin-associated periodic syndrome (CAPS) is a group of autoinflammatory diseases characterized by autosomal dominant mutations in NLRP3." (PMID 38042791, 2023). "Muckle-Wells syndrome (MWS) is an autosomal dominant autoinflammatory disease recognized as the intermediate phenotype of cryopyrin-associated periodic syndrome (CAPS) caused by NLRP3 gene mutation." (PMID 36873639, 2023). "Increased extracellular Ca2+ concentrations trigger activation of the NLRP3 inflammasome in monocytes through Ca2+-sensing receptor (CaSR) which causes inflammation in human cryopyrin-associated periodic syndrome (CAPS)." (PMID 36195671, 2023). "Gain-of-function mutation in NLRP3 causes a spectrum of autoinflammatory diseases termed cryopyrin-associated periodic syndromes (CAPS)." (PMID 36891515, 2023). "Cryopyrin-associated periodic syndrome (CAPS) is caused by gain-of-function mutations in the inflammasome sensor NLRP3 that trigger excessive inflammasome activation." (PMID 37939552, 2023).
cryopyrin-associated periodic syndrome (continued). "For example, SNP rs35829419 has been associated with increased NLRP3 inflammasome activation and the pathogenesis of cryopyrin-associated periodic syndromes (CAPS), characterized by recurrent fever and systemic inflammation." (PMID 37998389, 2023). "Human mutations in the NLRP3 gene have been reported to cause an autoinflammatory disease known as cryopyrin-associated periodic syndrome (CAPS), which shows systematic and joint inflammation with hyperactivation of the NLRP3 inflammasome." (PMID 35628185, 2022). "NLRP11 was also necessary for inflammasome responses driven by NLRP3 mutations that cause cryopyrin-associated periodic syndrome (CAPS)." (PMID 35624206, 2022). "Gain-of-function mutations in NLRP3 are associated with a series of rare autoinflammatory diseases (AIDs), collectively known as NLRP3-associated autoinflammatory diseases (NLRP3-AIDs), previously referred to as cryopyrin-associated periodic syndromes (CAPS)." (PMID 34671876, 2022). "In keeping with the concept of inflammasomopathies, cryopyrin-associated periodic syndromes (CAPS) are caused by gain-of-function (GOF) mutations in the NLRP3 gene." (PMID 36034552, 2022). "NOMID is the most severe clinical phenotype of a disease spectrum caused by gain-of-function mutations in NLRP3, called the Cryopyrin Associated Periodic Syndromes (CAPS)." (PMID 35601409, 2022). "The main attention given to the NLRP3 inflammasome has been due especially to its implication in the pathogenesis of several human inflammatory diseases, particularly of the cryopyrin-associated periodic syndromes (CAPS)." (PMID 35457026, 2022). "Recent studies revealed that variants of the NLRP3 gene cause genetic diseases, including systemic inflammatory syndrome called cryopyrin-associated periodic syndrome (CAPS) and non-syndromic sensorineural hearing loss DFNA34." (PMID 35572943, 2022). "The anti-inflammatory effects of 4-octyl-itaconate have also been reported in PBMCs isolated from CAPS (cryopyrin-associated periodic syndrome) patients and in an in vivo model of peritonitis induced by monosodium urate crystals as an NLRP3 activating signal." (PMID 34697412, 2022). "On the other hand, gain of function mutations in NLRP3 result in increased IL-1 [a defining feature of Cryopyrin-associated periodic syndrome (CAPS)]." (PMID 35401657, 2022). "NLRP3-related autoinflammatory disease (NLRP3-AID), previously called Cryopyrin-associated periodic syndromes are due to a gain-of-function mutation in NLRP3." (PMID 35411042, 2022). "For example, mutations in genes coding for components of the NLRP3 inflammasome lead to an AIFS called Cryopyrin-Associated Periodic Syndromes (CAPS)." (PMID 36552788, 2022). "Cryopyrin-associated periodic syndromes (CAPSs) are a group of autoinflammatory disorders caused by a mutation in the NLRP3 gene." (PMID 35281325, 2022). "The cryopyrin-associated periodic syndromes (CAPS) are autoinflammatory disorders caused by various gain-of-function missense mutations of the NLRP3 gene." (PMID 33996748, 2021). "Cryopyrin associated periodic syndrome (CAPS) is a group of diseases related to a defect in the protein cryopyrin (NLRP3)." (PMID 34867986, 2021). "Mutations in the NLRP3 gene are known to cause an autoinflammatory disease called cryopyrin-associated periodic syndrome (CAPS)." (PMID 33498715, 2021). "In humans, Nlrp3 gain-of-function mutations are causing a spectrum of rare auto-inflammatory disorders known as cryopyrin associated periodic syndromes (CAPS)." (PMID 35087852, 2021). "Mutations in NLRP3 are a well-known etiology of a series of autoinflammatory diseases, such as cryopyrin-associated periodic syndrome (CAPS)." (PMID 33534121, 2021). "The NLRP3 inflammasome was initially considered a molecular complex related to the autoinflammatory disease cryopyrin-associated periodic syndrome (CAPS) caused by a genetic mutation." (PMID 33671159, 2021).
cryopyrin-associated periodic syndrome (continued). "Gain-of-function mutations in exon 3 of the NLRP3 gene have been implicated in hereditary auto-inflammatory diseases, grouped under Cryopyrin-associated periodic syndrome (CAPS), suggesting the presence of functionally-important sites in this region." (PMID 32477355, 2020). "The disease group is also known as Cryopyrin associated periodic syndromes (CAPS) but it has been proposed to rename the group to NLRP3-AID, to reflect the name of the gene over its encoded protein." (PMID 32019685, 2020). "NLRP3 inflammasome signaling is implicated in the onset of a number of diseases, including gout, atherosclerosis, type ІІ diabetes, Cryopyrin-associated periodic syndrome (CAPS), various types of cancer, and inflammatory bowel disease (IBD)." (PMID 33424869, 2020). "NLRP3 was initially characterized as a major causative factor of inflammation owing to NLRP3’ involvement in a group of rare heterogeneous autoinflammatory conditions, known as cryopyrin-associated periodic syndrome." (PMID 32012695, 2020). "Several NLRP3 mutations result in constitutive activation of the NLRP3 inflammasome, causing cryopyrin-associated periodic syndrome (CAPS)." (PMID 32782316, 2020). "The NLRP3 inflammasome has been widely studied and its constitutive activation is associated with autoinflammatory diseases caused by gain-of-function mutations in the NLRP3 gene, known as Cryopyrin associated periodic syndromes (CAPS)." (PMID 31333677, 2019). "Accordingly, NLRP3 gain-of-function mutations, which cause a spectrum of autoinflammatory disorders known as cryopyrin-associated periodic syndromes (CAPS), are associated with excessive IL-1β and IL-18 production." (PMID 30388107, 2018). "Inhibition of NLRP3 by MCC950 effectively rescued neonatal lethality in a mouse model of cryopyrin-associated periodic syndrome, a genetic disease caused by activating mutation in NLRP3." (PMID 29872077, 2018). "Consistent with the NLRP3 inflammasome role in interleukin (IL)-1β and IL-18 maturation, cryopyrinopathies are associated with excessive production of these cytokines." (PMID 30388107, 2018). "Cryopyrin-associated periodic syndromes (CAPS) typically represent the autoinflammatory mechanisms associated with gain-of-function mutations in the NLRP3 gene, which result in increased constitutive activity of the intracellular sensor protein." (PMID 30386349, 2018). "Heterozygous mutations in the NLRP3 gene in patients with cryopyrin associated periodic syndrome (CAPS) lead to hyper-responsive inflammasome function." (PMID 29322034, 2017). "Cryopyrin-associated periodic syndrome (CAPS) patients with NLRP3 mutations have autoinflammation in skin, joints, and eyes, but not in the intestine." (PMID 29196621, 2017). "Cryopyrin-associated periodic syndromes are disorders caused by mutations in the NLRP3 gene, previously known as cold-induced autoinflammatory syndrome 1, which results in uncontrolled processing of IL-1β and IL-18." (PMID 28588486, 2017). "Originally, NLRP3 was identified as a responsible gene for cryopyrin-associated periodic syndrome (CAPS), which includes three syndromes with differing severity." (PMID 29259717, 2017). "Mutations in the gene encoding for NLRP3 have been linked to autoinflammatory syndromes (cryopyrinopathies) associated with aberrant IL-1β production, which have been further characterized by mouse models of mutant NLRP3." (PMID 26385789, 2015). "It is noteworthy that periodic fever is a main symptom of cryopyrinopathies, a human inflammatory disorder that is associated with mutations in both NLRP3 and NLRP12 genes." (PMID 24453977, 2014). "Mutations in the NLRP3 gene are associated with the dominantly inherited cryopyrin-associated periodic syndrome (CAPS)." (PMID 23421920, 2013).
cryopyrin-associated periodic syndrome (continued). "Cryopyrin-associated periodic syndrome cases diagnosed in adulthood have been reported and common inflammasome-related NLRP3 and CARD8 polymorphisms have been described, although without evidence on disease susceptibility." (PMID 24138840, 2013). "Using this system, the expression of NLRP3 mutants in cryopyrin-associated periodic syndrome (CAPS) patients was sufficient for the induction of necrotic cell death without lipopolysaccharide stimulation or generation of mature IL-1β." (PMID 23703389, 2013). "Cryopyrin-associated periodic syndromes (CAPS) are systemic auto-inflammatory diseases that appear to depend on heterozygous mutations in the gene encoding NALP3, i.e. NLRP3 (Gen Bank: NG 007509.2) (reviewed in:)." (PMID 22403613, 2012). "Mutations in NLRP3 are responsible for the cryopyrinopathies, a spectrum of conditions including neonatal-onset multisystem inflammatory disease (NOMID)." (PMID 22558291, 2012). "MCC950 was found to effectively hinder the activation of the NLRP3 inflammasome and the subsequent release of interleukin-1β, leading to a significant reduction in mortality rates in mice with cryopyrin-associated periodic syndrome, a condition caused by abnormal NLRP3 inflammasome activation." (PMID 38671903, 2024). "Interestingly, NLRP3 activation has been associated with the pathogenesis of certain inflammatory conditions, including cryopyrin-associated periodic syndromes (CAPS), Alzheimer’s disease, diabetes, gout, autoinflammatory disease, and atherosclerosis." (PMID 38623843, 2024). "However, overactivation of the NLRP3 inflammasome contributes to the development of various inflammatory diseases, including Alzheimer’s disease, cryopyrin-associated periodic syndromes (CAPS), gout, autoinflammatory diseases, and atherosclerosis." (PMID 36680009, 2023). "Mutations in NLRP3 cause autoinflammatory cryopyrin-associated periodic syndromes (CAPS)." (PMID 36127465, 2022). "Cryopyrin-associated periodic syndrome-associated NLRP3 mutants form cryo-sensitive foci." (PMID 35616535, 2022). "Cryopyrin-associated periodic syndrome-associated NLRP3 mutants form aggregates." (PMID 35616535, 2022). "Mutations in the gene encoding NLRP3 cause cryopyrin-associated periodic syndromes (CAPS)." (PMID 33007998, 2020). "Gain of function mutations of NLRP3 genes cause cryopyrin associated periodic syndromes (CAPS)." (PMID 32560261, 2020). "For instance, Cryopyrin-associated periodic syndromes (CAPS) are caused by gain-of-function mutations in the NLRP3 gene that result in the constitutive activation of the NLRP3 inflammasome and the release of IL-1β, in turn responsible for the symptomatology of the disease." (PMID 32796686, 2020). "Additionally, NLRP3 gain-of-function point mutations cause systemic periodic fever syndromes that are collectively known as cryopyrin-associated periodic syndrome (CAPS)." (PMID 31525186, 2019). "Interestingly, PKD inhibition in cells from patients with cryopyrin-associated periodic syndrome (who exhibit spontaneous NLRP3 oligomerisation) also showed reduced NLRP3 activation." (PMID 31131091, 2019). "Examples are MEFV/pyrin in familial Mediterranean fever (FMF), TNFRSF1A/TNF receptor type 1 in TNF receptor-associated periodic syndrome (TRAPS), and nucleotide-binding domain, leucine-rich-containing family, pyrin domain-containing 3 (NLRP3) in cryopyrin-associated periodic syndromes (CAPS)." (PMID 28421072, 2017). "The mutation in the gene (currently called NLRP3-inflammasome) in recurrent and chronic inflammation was initially detected in a group of rare autoinflammatory conditions, termed cryopyrin-associated periodic syndromes (CAPS); this protein also belongs to the pyrin family." (PMID 28588495, 2017).
cryopyrin-associated periodic syndrome (continued). "Recombinant oligomeric protein particles composed of the adaptor ASC or the p.D303N mutant form of NLRP3 associated with cryopyrin-associated periodic syndromes (CAPS) stimulate further activation of caspase-1 extracellularly, as well as intracellularly after phagocytosis by surrounding macrophages." (PMID 27842563, 2016). "Indeed, an NLRP3 gene mutation has been shown to induce autoinflammatory diseases such as cryopyrin-associated periodic syndrome (CAPS) and to alter the basal redox state of monocytes of patients with CAPS." (PMID 25389767, 2014). "Similarly, mutations in the NOD of the inflammasome forming protein NLRP3 result in hyper- or auto-activation of the receptor and lead to development of a spectrum of inflammatory diseases collectively known as cryopyrin associated periodic syndromes." (PMID 24598002, 2014). "In light of the recent findings that connect autophagy and inflammasome regulation, it remains to be determined whether alterations in autophagy could explain, at least in part, the dysregulated production of IL-1β in NLRP3-associated cryopyrinopathies." (PMID 24273538, 2013). "Cryopyrin-associated periodic syndromes are a group of autoinflammatory diseases transmitted by autosomal dominant inheritance caused by mutations in the NLRP3 gene (also called CIAS1 or PYPAF) encoding for cryopyrin, a crucial inflammasome protein that directly activates IL-1β." (PMID 24282415, 2013). "Among the autoinflammatory syndromes, cryopyrin-associated periodic syndromes (CAPS) are conditions associated with mutations of the NLRP3 gene, also known as CIAS1 or PYPAF1, a key component of the inflammasome directly involved in the mechanism of interleukin-1β (IL-1β) processing and secretion." (PMID 21360512, 2011). "Cryopyrin-associated periodic syndrome (CAPS) gain-of-function NLRP3 mutants have a higher affinity for oxidized DNA7,8." (PMID 41571747, 2026). "Cryopyrin-associated periodic syndrome (CAPS) is an autoinflammatory disease caused by a gain-of-function mutation in the NLRP3 gene, which regulates inflammasome-mediated interleukin-1β (IL-1β) production." (PMID 40927711, 2025). "NLRP3-mediated pathogenic mechanisms were first identified in cryopyrin-associated periodic syndrome (CAPS), a hereditary autoinflammatory condition transmitted through dominant inheritance patterns." (PMID 40830103, 2025). "Patients with NLRP3 mutations suffer from Cryopyrin-Associated Periodic Syndrome (CAPS) emphasizing the clinical significance of modulating NLRP3." (PMID 39653810, 2025). "Heterozygous missense mutations in NLRP3 cause autosomal dominant cryopyrin-associated periodic syndromes (CAPS)." (PMID 40927711, 2025). "Aberrant activation of NLRP3, illustrated by Cryopyrin-Associated Periodic Syndromes (CAPS) caused by genetic mutations, underscores the importance of understanding and modulating its function." (PMID 39653810, 2025). "According to the consensus, the proposed nomenclature for cryopyrin-associated periodic syndrome (CAPS) was subsequently revised to NLRP3-associated AID based on a new understanding of the NLRP3 gene." (PMID 40852416, 2025). "Autosomal dominant (AD) gain-of-function mutations in the NLRP3 gene are known to cause cryopyrin-associated periodic syndrome (CAPS)." (PMID 40538939, 2025). "NLRP3 was identified through its association with a group of rare autoinflammatory diseases collectively known as cryopyrin-associated periodic syndrome (CAPS)." (PMID 41062723, 2025). "NLRP3, also known as Cold autoinflammatory syndrome 1 protein (CIAS1), cryopyrin, NACHT, LRR, and PYD domain-containing protein 3 (NALP3), was initially discovered for its role in cryopyrin-associated periodic syndrome (CAPS)." (PMID 39301197, 2024). "Cryopyrin-associated periodic syndrome (CAPS) is an autoinflammatory condition resulting from monoallelic NLRP3 variants that facilitate IL-1β production." (PMID 38321014, 2024).